MEX3A (mex-3 RNA binding family member A)
Diseases named in the same sentence as MEX3A in open-access papers (continued):
Sharing a sentence is not in itself a finding about the gene and the disease.
cancer (continued). "Our study provides a novel insight into the potential role of MEX3A as a cancer biomarker from the perspective of tumor immunology." (PMID 34189143, 2021). "In this context, the role of MEX3A have garnered increasing attention in cancer with emerging evidence." (PMID 33827584, 2021). "In this review, we discuss recent studies to emphasize emerging evidence for a pivotal role of the MEX3 protein family, in particular MEX3A, in human cancer." (PMID 34067172, 2021). "It has been studied that MEX3A (Mex-3 RNA Binding Family Member A) is involved in carcinogenesis by accelerating cancer proliferation and migration." (PMID 34486491, 2021). "Transcriptomic analysis of PDAC samples that were screened for homogenous cancer cell population using the Psycomics tool indicated that MEX3A, and to a lesser extent SRRM1, were expressed at significantly higher levels in basal‐like tumors." (PMID 33159833, 2021). "The correlations between MEX3A and cancer immune infiltration were analyzed by the Tumor Immune Estimation Resource (TIMER) site and the TISIDB database." (PMID 34189143, 2021). "In order to better understand the potential immune mechanism of MEX3A in cancer, genetic variations of MEX3A retrieved from the TCGA database (489 cases, Nature 2011) were analyzed by using the cBioPortal database." (PMID 34189143, 2021). "Firstly, to determine differences in MEX3A expression in tumor and normal tissues, the MEX3A mRNA levels in different tumors and normal tissues of various cancer types were analyzed using the Oncomine database." (PMID 34189143, 2021). "MEX3A promotes cell proliferation in bladder and gastric cancer and shows potential as a biomarker to predict carcinogenesis." (PMID 31998552, 2020). "MEX3A is an RNA-binding proteins (RBPs) that promotes the proliferation, invasion, migration and viability of cancer cells." (PMID 31998552, 2020). "In intestinal adult stem cells, MEX3A is required for cell self-renewal and when overexpressed, MEX3A can contribute to support the proliferation of different cancer cell types." (PMID 33072742, 2020). "Since we previously demonstrated in cancer cell lines that MEX3A post‐transcriptionally represses the expression of caudal‐type homeobox 2 (CDX2) protein 39, a master regulator of intestinal maturation, we assessed CDX2 expression in the mutant animals." (PMID 32052574, 2020). "The analysis of IPA disease & function indicated that the most favorable one regulated by MEX3A was cancer." (PMID 33188661, 2020). "The normalized fold change of mex3a mRNA in cancer and normal tissues ranged from 0.89 to 151.22, and the mean fold change was 31.75 ± 46.75." (PMID 28903380, 2017). "In conclusion, the expression level of mex3a was higher in cancer tissues compared with normal adjacent tissues." (PMID 28903380, 2017). "The result of logistic regression suggests that the cancer subtype strongly affects mex3a expression." (PMID 28903380, 2017). "It was demonstrated that the mean normalized expression of mex3a was 1191.153 ± 1556.508 in cancer and 167.466 ± 323.095 in adjacent normal tissues." (PMID 28903380, 2017). "Among the MEX3 family members, MEX3A has been found overexpressed in several human malignancies and recently it has emerged as a promising biomarker and therapeutic target in a wide range of cancers." (PMID 40958871, 2025). "To date, this is the first investigation into the MEX3A-circRNAs network in cancer." (PMID 38565536, 2024). "Given the parallels with our findings, therapeutically targeting ubiquitylation enzymes like MEX3C and MEX3A may hold promise as an innovative strategy to suppress tumorigenesis in cancers where they play an oncogenic role." (PMID 38424632, 2024). "We found that both the frequency and the size of colonies growing in an anchorage-independent manner, which is a hallmark of oncogenic transformation 33, markedly increased in response to MEX3A, suggesting enhanced stemness and proliferative capacity of cancer stem cells." (PMID 36276637, 2022).
cancer (continued). "This suggests potentially important role for MEX3A in cancer stem cells." (PMID 36276637, 2022). "There is evidence that MEX3A is related to the occurrence of cancer." (PMID 35715407, 2022). "Considering that Mex3a promotes ISC stemness and become overexpressed in CRC, we hypothesized that MEX3A contributes to cancer progression." (PMID 36276637, 2022). "Given the fact that MEX3A participates in the degradation or inhibition of mRNA by ubiquitination, a lot of studies provided evidence that MEX3A played an important role in the occurrence and development of many diseases including cancer." (PMID 33414423, 2021). "Accordingly, ectopic MEX3A expression could enforce proliferation and thus promote cell vitality in cancer and serve as a marker of dismal disease outcome." (PMID 34067172, 2021). "It is unclear whether targeting MEX3A could influence the recruitment numbers of TIICs to impact the prognosis of cancers." (PMID 34189143, 2021). "MEX3A is a critical RNA-binding ubiquitin ligase that is upregulated in various types of cancer." (PMID 34189143, 2021). "Moreover, a recent screening of 1542 human RBPs dysregulated across 15 cancer types indicated that MEX3A is up‐regulated in multiple epithelial cancers." (PMID 33159833, 2021). "Studies have found that MEX3A is involved in the pathogenesis of cancer." (PMID 34486491, 2021). "One could speculate that chromosomal gain of 1q triggers (re-)expression of the oncofetal MEX3A in various cancer entities." (PMID 34067172, 2021). "The MEX3A‐mediated regulation of PPARγ signalling might also have a yet undisclosed significance for intestinal pathologies, namely cancer initiation/progression." (PMID 32052574, 2020). "As one of the MEX3 homologous genes, MEX3A also participates in the regulation of mRNA and may mediate the occurrence and development of many diseases, such as cancer." (PMID 33188661, 2020). "As one of the MEX3 homologous genes, MEX3A participates in the regulation of mRNA and may be involved in the occurrence and development of many diseases, including cancer." (PMID 33188661, 2020). "The results of the independent sample t-test revealed significant differences in the expression of mex3a between cancer tissues and adjacent normal tissues and this result led us to evaluate whether mex3a was a biomarker of BLCA and whether mex3a could affect the overall survival of BLCA patients." (PMID 28903380, 2017). "Therefore, the effect of the cancer subtype on the expression of mex3a in the multivariate Cox model might be an important confounding factor." (PMID 28903380, 2017). "Mex3a is an RNA-binding protein (RBP) that promotes the invasion, proliferation, migration, and viability of cancer cells." (PMID 39564121, 2024). "Our data elucidated that the function of MEX3A in suppressing CRC cell autophagy relies on the PDE5A pathway, providing the first evidence of PDE5A as a critical regulator in cancer cell autophagy." (PMID 38565536, 2024). "In this study, we found that MEX3A becomes ectopically upregulated in CRC and correlates with low grade cancer differentiation and poor survival prognosis." (PMID 36276637, 2022). "Our work demonstrates that E2F3-induced MEX3A directly suppresses terminal differentiation regulator KLF4 to activate WNT signaling, that in turn sustains cancer cells in rapidly-dividing and undifferentiated state." (PMID 36276637, 2022). "To further examine the direct impact of MEX3A on cancer cell stemness, we measured anchorage-independent growth of HCT116 cells upon MEX3A overexpression." (PMID 36276637, 2022). "Nevertheless, relatively little is known on the oncogenic functions of MEX3A and even less on the molecular mechanisms modulated by this RBP in cancer cells." (PMID 33159833, 2021).
cancer (continued). "Calcitriol increases the expression of stemness-related genes, such as the leucine-rich repeat-containing G protein-coupled receptor 5 (LGR5), SMOC2, LRIG1, MEX3A, MSI1, and PTK7, attenuating the transformation into cancer stem cells, and, therefore, impacts tumorigenesis at a very early stage." (PMID 36364774, 2022). "Furthermore, it was recently reported that high expression of MEX3A correlates with advanced PDAC stage and worse prognosis in patients, indicating its oncogenic function in this cancer." (PMID 33159833, 2021). "A large proportion (47 RBPs) are commonly regulated in both RSCC and LSCC with several enriched for binding among DEGs (adj p < 0.05), including RBPs previously discussed in the context of CRC such MSI2, MEX3A, IGF2BP1/3, ELVAL4, and cancers in general, such as RBM47, DKC1, CELF4, ELAVL3." (PMID 32293332, 2020). "Furthermore, the Cancer Cell Line Encyclopedia (CCLE) and the European Bioinformatics Institute (EMBL-EBI) bioinformatics website were also used to test the expression of MEX3A in BC cell lines, and results indicated that MEX3A was increased in most cell lines of BC." (PMID 37433992, 2023). "Targeting MEX3A or KLF4 not only suppressed CRC cell proliferation, but also increased their differentiation status, suggesting that it might represent a new potent target for cancer differentiation therapy upon CRC." (PMID 36276637, 2022).
tumor (33 papers, 2017 to 2026). "The results showed that high expression of MEX3A was positively associated with tumor grade, stage and lymph node metastasis." (PMID 38914858, 2024). "Univariate analysis showed that high expression of MEX3A was associated with gender, tumor differentiation, depth of invasion, lymph node metastasis, distant metastasis and vessel or nerve invasion (P < 0.05)." (PMID 38914858, 2024). "Collectively, our findings revealed the important role of MEX3A and provided a novel target and a valuable insight into the underlying mechanism between MEX3A and tumor-immune interactions in OC." (PMID 34189143, 2021). "Despite obviously activating signaling pathways, MEX3A affects several tumor-associated genes, presumably, post-transcriptionally." (PMID 34067172, 2021). "In agreement, transcriptome studies revealed elevated expression of MEX3A in various tumors and association with tumor staging, grading, as well as overall survival probability." (PMID 34067172, 2021). "High expression of MEX3A was found to be correlated with more advanced tumor stage, higher risk of lymphatic metastasis and poor prognosis." (PMID 33188661, 2020). "In addition, increased expression of MEX3A in NSCLC patients was associated with stage I tumour and lymph node status and male sex, and chemotherapy had little effect on this prognosis." (PMID 36507941, 2023). "Histological analysis revealed marked reduction in tumor lesions upon Mex3a deficiency." (PMID 36276637, 2022). "MEX3A was first identified in nematodes and was associated with tumor formation and may promote cell proliferation and tumor metastasis." (PMID 32140076, 2020). "The statistical analysis of the relationship between MEX3A expression with tumor characteristics showed that high MEX3A expression was associated with advanced tumor stage and higher risk of lymphatic metastasis (P < 0.01), which was further verified by Spearman rank correlation analysis (P < 0.01)." (PMID 33188661, 2020). "Moreover, MEX3A high expression was positively associated with advanced tumor stage, higher risk of lymphatic metastasis and shorter survival period." (PMID 33188661, 2020). "The gene mex3a is associated with tumor formation and may promote cell proliferation and tumor metastasis." (PMID 28903380, 2017). "Importantly, these findings were further validated at protein level by IHC analysis performed on the available patient-derived GB and peritumoral tissue samples, confirming the elevated expression of MEX3A in tumor tissues, and its diagnostic and prognostic potential in GB." (PMID 40958871, 2025). "Therefore, our findings have uncovered a brand-new mechanism underlying MEX3A-induced tumor progression and might hint an auxiliary target for advancing CRC pharmacological therapies." (PMID 38565536, 2024). "The gene mex3a is associated with tumor formation and may promote cell proliferation and migration." (PMID 28903380, 2017). "Accordingly, MEX3A expression increases with higher tumor grade and was significantly associated with vital status." (PMID 40958871, 2025). "Animals that received MEX3A-depleted cells showed a reduced tumor size and a longer OS compared to control mice." (PMID 40958871, 2025). "Acting through its RNA-binding and E3 ubiquitin ligase domains, MEX3A appears to influence several pathways relevant to tumor progression and therapy resistance." (PMID 40958871, 2025). "Other slow-cycling populations characterized by MEX3A expression suppress Wnt signaling to evade chemotherapy and dominate the residual tumor mass post-treatment." (PMID 41002429, 2025). "In the subcutaneous xenograft model, MEX3A knockdown substantially reduced the in vivo tumorigenicity and tumor weights." (PMID 38565536, 2024).
tumor (continued). "We found that MEX3A was significantly upregulated and correlated to tumor stage and lymph nodal metastasis in CRC through bioinformatics analysis and tissue immunohistochemistry (IHC)." (PMID 38914858, 2024). "A subcutaneous tumor mouse model was constructed to analyze in vivo growth of BC cells after MEX3A knockdown." (PMID 37433992, 2023). "In LUSC, MEX3A was similarly shown to be positively correlated with tumour purity and B cells and negatively correlated with CD4+ T cells." (PMID 36507941, 2023). "In this study, we found that expression of MEX3A was noticeably elevated in tumor tissues and cell lines of BC, which in accordance with the analysis of TCGA and GEO database." (PMID 37433992, 2023). "Subsequent in vitro studies demonstrated that MEX3A knockdown inhibited BC cells proliferation and migration, as well as xenograft tumor growth in vivo." (PMID 37433992, 2023). "In LUAD, MEX3A was positively correlated with tumour purity and negatively correlated with the level of dendritic cell infiltration." (PMID 36507941, 2023). "In vitro experiments show that MEX3A depletion appreciably suppresses BC cell proliferation and invasion, implying MEX3A quite likely being a tumor promoter." (PMID 37433992, 2023). "Together, these findings demonstrate that MEX3A promotes tumor growth by enhancing the proliferative capacity of CRC cells." (PMID 36276637, 2022). "MEX3A is upregulated in EC and promotes tumor progression by activating EMT and regulating the Wnt/β-catenin pathway via DVL3." (PMID 36614043, 2022). "Taken together, these data suggest that MEX3A functions as an oncogene in retaining stemness and rapidly-dividing status of tumor cells." (PMID 36276637, 2022). "That inhibition of MEX3A suppressed proliferative capacity of tumor cells and forced their differentiation, while MEX3A overexpression promoted it, highlighting its pro-tumorigenic role in CRC." (PMID 36276637, 2022). "It suggests that Mex3a functions as an oncogene in retaining stemness and rapidly-dividing status of tumor cells." (PMID 36276637, 2022). "MEX3A knockdown strongly inhibited formation and growth of HCT116 tumor spheroid (diameter ≥ 50 μm), conversely MEX3A overexpression promoted it." (PMID 36276637, 2022). "Accordingly, the percentage of CD44+ cells and SOX2+ cells reduced in tumor spheroids upon MEX3A knockdown, while they increased upon MEX3A overexpression." (PMID 36276637, 2022). "To investigate the role of MEX3A in EC, we first detected the expression pattern of MEX3A in different normal and tumor tissues from TCGA." (PMID 36614043, 2022). "Meanwhile, the expression profiling data collected from The Cancer Genome Atlas (TCGA) also demonstrated a 10.7-fold higher MEX3A expression in tumor tissues relative to normal tissues (P < 0.001)." (PMID 33414423, 2021). "Recently several studies analyzed the function of MEX3A in the context of different tumor types, demonstrating in vitro functions of MEX3A in promoting cell proliferation and migration, as well as inhibiting apoptosis." (PMID 34067172, 2021). "Based on immunohistochemistry and RNA expression data, MEX3A was therefore suggested as a prognostic tumor marker in various studies." (PMID 34067172, 2021). "In this study, we found that expression of MEX3A was significantly upregulated in ESCC tumor tissues compared with normal tissues, which was in consistent with data mining of TCGA." (PMID 33188661, 2020). "the mice that received Mex3a-knockdown H1299 cell resulted in a significant inhibition of tumor growth and tumor weight." (PMID 32792503, 2020). "It was demonstrated that MEX3A expression was significantly elevated in tumor tissues compared with normal tissues (P < 0.001)." (PMID 33188661, 2020). "The RNA-binding ubiquitin ligase MEX3A was found up-regulated in GB specimens, and this correlates with low protein levels of the tumor-suppressor RIG-I." (PMID 32019099, 2020).